FZD7 (frizzled class receptor 7)
Diseases named in the same sentence as FZD7 in open-access papers (continued):
Sharing a sentence is not in itself a finding about the gene and the disease.
renal cell carcinoma (2 papers, 2021). "miR-613 is predicted to bind the Fzd7 3′UTR and decreases Fzd7 expression when transfected into renal cell carcinoma cell lines." (PMID 34671643, 2021).
seminoma (2 papers, 2015 to 2023). A radiosensitive malignant germ cell tumor found in the testis (especially undescended), and extragonadal sites (anterior mediastinum and pineal gland). "Among them, GDF3, NODAL, LEFTY1 /2, GAL, DPPA3, SOX2, DNMT3B /L, DPPA5, BCAT1, FGF2, PRDM14, ZIC3 and FZD7, while seminoma markers SOX17, cKIT and PRAME were downregulated." (PMID 26226633, 2015). "Accordingly, WNT3 /5B and FZD7 expression is higher in EC tissues than in CIS /seminomas." (PMID 26226633, 2015). "Furthermore, additional EC and pluripotency genes were upregulated (SOX2, LEFTY1 /2, DNMT3L, SALL4, DPPA5, BCAT1, FZD7, LIN28, ZIC3), while seminoma-associated genes where downregulated (SOX17, TFAP2C, cKIT, PRAME), without changing 5mC-levels." (PMID 26226633, 2015). "However, we also observed significant associations between high expression of WNT activators (e.g., CTNNB1, FZD1, and FZD7) and poor survival of type II non-seminoma GCT patients, suggesting WNT signaling may be a common driver of adverse outcome in GCT patients across age groups." (PMID 37149691, 2023).
serous ovarian tumors (2 papers, 2024). "Moreover, TCGA datasets confirmed that combined expression of ILK and Fzd7 in high grade serous ovarian tumors is correlated with reduced response to chemotherapy and poor patient outcomes." (PMID 38559125, 2024).
squamous cell carcinoma (2 papers, 2018 to 2022). A carcinoma arising from squamous epithelial cells. "We found a group of tumor-specific WNT members, including a panel of squamous cell carcinomas (SCCs) specific upregulated WNT ligands and receptors, WNT5A, WNT7B, FZD7 and GPC1." (PMID 35850748, 2022).
adenoma (1 paper, 2022). A neoplasm arising from the epithelium. "Interestingly, in invasive adenomas compared to the normal pituitary gland (GSE51618) FZD7 was also found to be downregulated." (PMID 35203352, 2022).
asthma (1 paper, 2024). "Indeed, several genes identified in this study are enriched in WNT/beta-catenin signaling, including FZD7 and HNF1A, suggesting methylation signals associated with the activation WNT/beta-catenin signaling in the development of asthma pathology." (PMID 38245772, 2024).
attention deficit-hyperactivity disorder (1 paper, 2014). A disorder characterized by a marked pattern of inattention and/or hyperactivity-impulsivity that is inconsistent with developmental level and clearly interferes with functioning in at least two settings (e.g. at home and at school). "YWHAZ is cocited with FZD7 in a paper on attention-deficit/hyperactivity disorder, with ATXN1 in a paper on the interaction of Akt-Phosphorylated Ataxin-1 with 14-3-3, and with SOS2 in a paper on epidermal growth factor receptor phosphorylation sites." (PMID 25148247, 2014).
brain edema (1 paper, 2021). Increased intracellular or extracellular fluid in brain tissue. "Activation of FZD7 reduced brain edema and improved limb placement test compared to the ICH control group (p < 0.05) and FZD7 activation improved brain edema and neurological scores in Garcia and limb placement tests compared with FZD7 knockdown group 24 h post-ICH (p < 0.05)." (PMID 34565396, 2021).
Cerebral ischemia (1 paper, 2025). Restriction of arterial blood supply to the brain associated with insufficient oxygenation to support the metabolic requirements of the tissue. "In particular, elevated levels of the FZD7 protein align with other studies implicating activation of Wnt signaling after cerebral ischemia." (PMID 41091415, 2025).
colitis (1 paper, 2023). Inflammation of the colon. "Additionally, loss of Fzd7 exacerbated the defects in a chemical-induced colitis model and could initiate tumorigenesis." (PMID 36691900, 2023).
Crohn disease (1 paper, 2023). A gastrointestinal disorder characterized by chronic inflammation involving all layers of the intestinal wall, noncaseating granulomas affecting the intestinal wall and regional lymph nodes, and transmural fibrosis. "Our findings suggest that FZD7 may be involved in the pathogenesis of pediatric Crohn’s disease, potentially through its role in the regulation of these processes." (PMID 36936436, 2023).
Duchenne muscular dystrophy (1 paper, 2021). Duchenne muscular dystrophy (DMD) is a neuromuscular disease characterized by rapidly progressive muscle weakness and wasting due to degeneration of skeletal, smooth and cardiac muscle. "Accordingly, therapeutic stimulation of WNT7a/FZD7 by injection of recombinant Wnt7a resulted in a significant increase in muscle strength and a reduce contractile damages in mdx mice (Duchenne Muscular Dystrophy (DMD) model)." (PMID 33466753, 2021).
embryonic carcinoma (1 paper, 2016). "Wnt/β-catenin signaling is one of the key signalling pathways shown to regulate FZD7 expression, as FZD7 expression is increased in human embryonic carcinoma cells following exposure to Wnt3a conditioned medium." (PMID 27196929, 2016).
enterocolitis (1 paper, 2023). An inflammatory process affecting the small intestine and colon. "Conclusively, Fzd7 has important functions in maintaining the regular differentiation and homeostasis of the intestinal epithelium, and loss of Fzd7 function is a crucial issue in the pathogenesis of enterocolitis, as well as in the formation of tumors." (PMID 36691900, 2023). "The Fzd7 conventional knockout model, which was generated in our lab, was analyzed from 3 weeks to 12 months of age to confirm that Fzd7 deficiency causes severe enterocolitis and other phenotypes with time." (PMID 36691900, 2023). "All these phenotypes drive the process of enterocolitis, and related features were observed in Fzd7 KO mice." (PMID 36691900, 2023). "Fzd7 deletion interferes with intestinal regeneration and differentiation, contributing to the pathogenesis of enterocolitis." (PMID 36691900, 2023). "Several phenotypes in our Fzd7-deleted model were similar to the features of enterocolitis, such as shortened intestines, decreased numbers of goblet cells and Paneth cells, and severe inflammation." (PMID 36691900, 2023).
hematoma (1 paper, 2021). A hematoma is a collection of blood from a vascular structure into an extravascular space. "Nevertheless, the effect of FZD7 activation on post-ICH hematoma resolution needs to be further investigated." (PMID 34565396, 2021). "At 72 h after ICH, activation of FZD7 reduced both Evans blue leakage and hematoma volume compared with ICH + Ctrl group (p < 0.05)." (PMID 34565396, 2021). "Third, the effects of FZD7 signaling on angiogenesis and hematoma resolution after ICH needs to be investigated in future studies." (PMID 34565396, 2021). "We speculated that early FZD7 activation may facilitate beneficial angiogenesis process and thereby promote hematoma resolution." (PMID 34565396, 2021).
idiopathic pulmonary fibrosis (1 paper, 2012). Idiopathic pulmonary fibrosis (IPF) is a nonneoplastic pulmonary disease that is characterized by the formation of scar tissue within the lungs in the absence of any known cause. "Studies in animal models, as well as in human disease, have identified several components of the canonical WNT signaling pathway, including WNT2, FZD7, LRP6, β-CATENIN and GSK-3β which are overexpressed in idiopathic pulmonary fibrosis (IPF)." (PMID 22846383, 2012).
injury (1 paper, 2021). Damage inflicted on the body as the direct or indirect result of an external force, with or without disruption of structural continuity. "Thus, our findings provide evidence supporting the importance of Fzd7 in the development of radiation-induced brain injury." (PMID 34595206, 2021).
Insulin resistance (1 paper, 2019). Increased resistance towards insulin, that is, diminished effectiveness of insulin in reducing blood glucose levels. "WNT inhibitory factor 1 (WIF1), FZD7, and ROR2 are novel biomarkers for the development of insulin resistance." (PMID 30678306, 2019).
intestinal tumors (1 paper, 2025). "In order to target FZD7, a potential target for the treatment of intestinal tumors, we combine an approach of adapted docking setups and large molecular library docking screens, identifying compound C407." (PMID 41392205, 2025).
kidney stone (1 paper, 2025). "Additionally, the findings of the CIBERSORT investigation indicated that FZD7 and SUV39H1 may be linked to variations in the immune milieu of people who have kidney stones." (PMID 40171220, 2025). "Among these, the expression of SUV39H1 and LCN2 was higher in the kidney stone model than in normal samples (p < 0.001), but the expression of FZD7 and STK11 was lower in the kidney stone model (p < 0.001)." (PMID 40171220, 2025). "Consistent with in vitro results, the expression of SUV39H1 and LCN2 was higher and the expression of FZD7 and STK11 was lower in the kidney stone model than in normal samples (p < 0.001)." (PMID 40171220, 2025). "However, FZD7 has not been studied and reported in kidney stone." (PMID 40171220, 2025).
liver fibrosis (1 paper, 2022). "In particular, Wnt5a is involved in the liver degeneration, being overexpressed in liver fibrosis, which presents FZD2 and FZD7 as receptor." (PMID 35334792, 2022).
lymph node metastasis (1 paper, 2025). "Elevated expression of FZD7 is linked to an elevated incidence of GC and increased lymph node metastasis." (PMID 40943055, 2025). "Moreover, FZD7 overexpression, poor tumor differentiation, lymph node metastasis, and advanced TNM stage were associated with worse outcomes." (PMID 40943055, 2025).
mental disorder (1 paper, 2018). A disease that has its basis in the disruption of mental process. "We show for the first time in a large sample that the mRNA expression of FZD7 and NFATC3, two highly relevant Wnt signaling pathway genes, is significantly increased in patients with severe mental disorders compared to HCs." (PMID 29507296, 2018).
metastatic melanoma (1 paper, 2016). A melanoma that has spread from its primary site to another anatomic site. "Regulation of metastasis by FZD7 in all four lines suggest that this may be a shared mechanism among metastatic melanomas." (PMID 26808375, 2016).
neuroblastoma (1 paper, 2021). Neuroblastoma (NB) is the most common solid, extracranial childhood tumor. "In neuroblastoma N2a cells, the Wnt3 intensity at the cell membrane decreases with the Fzd7 downregulation." (PMID 33525513, 2021).
non-small cell lung carcinoma (1 paper, 2020). A group of at least three distinct histological types of lung cancer, including non-small cell squamous cell carcinoma, adenocarcinoma, and large cell carcinoma. "OMP-18R5 (Vantictumab) targets the FZD1, FZD2, FZD5, FZD7, and FZD8 frizzled protein receptors to block WNT signaling are being investigated in phase I clinical trials in breast, pancreatic, and non-small cell lung cancer." (PMID 32758244, 2020).
nonalcoholic fatty liver disease (1 paper, 2022). "In another study, researchers utilized plasma-derived exosomes containing FZD receptor protein (FZD7) to modulate the dysregulated Wnt/Frizzled (FZD) signaling in nonalcoholic fatty liver disease (NAFLD)." (PMID 36195966, 2022).
oesophageal cancer (1 paper, 2016). "Human FZD7 was first identified and characterised in 1998, and was also discovered to be upregulated in oesophageal cancer by a different group in the same year, who named it FzE3." (PMID 27196929, 2016).
ovarian serous cystadenocarcinoma (1 paper, 2023). A malignant serous cystic epithelial neoplasm arising from the ovary. "Ovarian serous cystadenocarcinoma overexpresses the Wnt receptor FZD7." (PMID 37190019, 2023). "Thus, FZD7 could be a tumor-specific antigen in ovarian serous cystadenocarcinoma." (PMID 37190019, 2023).
pancreatic adenocarcinoma (1 paper, 2021). "And in the ONCOMINE database, Fzd7 was significantly overexpressed in pancreatic adenocarcinoma compared with other Frizzled receptors." (PMID 33934523, 2021).
pancreatic ductal adenocarcinoma (1 paper, 2022). An infiltrating adenocarcinoma that arises from the epithelial cells of the pancreas. "In pancreatic ductal adenocarcinoma patients, high FZD7 expression associated with earlier hepatic metastases." (PMID 35854234, 2022). "The expression of Frrizled receptor 7 (FZD7) in pancreatic ductal adenocarcinoma (PDAC) and relating survival rate were analyzed by bioinformatics, histochemistry assay and follow-up study." (PMID 35854234, 2022). "By Western blot, we confirmed that FZD7 was expressed in AsPC-1, Capan-2, PANC-1 and SW1990 cells to different degrees, of which PANC-1 was derived from pancreatic ductal adenocarcinoma." (PMID 35854234, 2022).
prostate tumors (1 paper, 2018). "Similar to FZD7, we found MEIS1 is down-regulated in both prostate tumors and PCa cell lines, and a high MEIS1 expression is an indication of better overall survival for PCa patients." (PMID 29416676, 2018).
psychotic disorder (1 paper, 2018). An abnormal condition of the mind that involves a loss of contact with reality. "If the dysregulated FZD7 signaling is also present in the neural tissues of patients with psychotic disorders, the promiscuity of FZD7 with regard to interactions with other receptors and multiple Wnt pathways make it an appealing candidate for further studies." (PMID 29507296, 2018).
rectal adenocarcinoma (1 paper, 2023). "In our study, Fzd7 KO mice with chronic DSS injury for only 90 days had the potential to develop rectal adenocarcinoma (1/8=12.5%)." (PMID 36691900, 2023).
steatosis (1 paper, 2022). Increased lipid within the cytoplasm of cells. "Furthermore, the grouping of patients according their steatosis grade revealed that FZD7 expression remained significantly upregulated in all the patient groups (p < 0.05)." (PMID 35334792, 2022).
testicular germ cell tumor (1 paper, 2017). A germ cell tumor arising from the testis. "Recently, miR-142 was demonstrated as a tumor initiation factor in cervical and testicular germ cell tumors by targeting FZD7." (PMID 28177895, 2017).
tumor (103 papers, 2008 to 2026). "Using genetically engineered mice carrying a humanized allele of Fzd7, we demonstrate that a FZD7-specific antibody (F7Ab) can reliably identify and isolate Fzd7-expressing tumor cells." (PMID 41218118, 2025). "YTH N6-methyladenosine RNA binding protein 1 (YTHDF1) was found to be positively associated with aggressive tumor progression and poor overall survival by promoting the translation of the essential Wnt receptor frizzled 7 (FZD7) in an m6A-dependent manner." (PMID 33816259, 2021). "FZD7 promotes tumor progression, and high expression of FZD7 is associated with poor survival only in male GBM patients." (PMID 34359952, 2021). "In GC, upregulation of FZD7 was detected and associated with tumor progression, metastasis, and poor prognosis." (PMID 31827644, 2019). "Among them, FZD7 has been considered a promising therapeutic target because FZD7 mediated Wnt/β-catenin signaling is closely associated with growth and survival of tumor cells." (PMID 21314951, 2011). "Likewise, miRNAs have been shown to influence the expression of Fzd7 in several different cancers, and associated with reduced tumour growth, which are discussed in the relevant cancer sections below." (PMID 27196929, 2016). "Furthermore, analysis of HGSOC tumor microarray data using OvMark demonstrated an increased estimated risk of death in patients with higher than median Fzd7 and ILK combined expression levels compared with patients with lower than median Fzd7 and ILK expression levels." (PMID 38822429, 2024). "This promiscuity of Fzd7 to associate with different co-receptors and regulate both arms of the Wnt pathway may explain its frequent up-regulation in many different cancers to drive tumour growth, as both pathways are implicated in cancer." (PMID 27196929, 2016). "Several high-scoring proteins, including ITGB8, LGR5, FZD7, HLA-E, ANGPTL2, and BST2 emerged as candidates potentially affected by protonation-linked perturbations in acidic tumor microenvironments." (PMID 42036641, 2026). "Despite the cellular heterogeneity of MMTV-Wnt1 tumors, treatment with a Fzd7-specific antibody–drug conjugate significantly suppresses tumor growth, suggesting that Fzd7-expressing cells are critical drivers of tumor progression." (PMID 41218118, 2025). "Endothelial cells in pre-metastatic niches can secrete Wnt ligands that interact with FZD7 on circulating tumor cells, enhancing their survival, adhesion, and outgrowth in distant tissues." (PMID 40376615, 2025). "We identify FZD7 as a key marker of tumor-initiating basal cells in the MMTV-Wnt1 mouse model of TNBC and demonstrate its value as a therapeutic target." (PMID 41218118, 2025). "Taken together, these findings establish FZD7 as a marker of tumor-initiating basal cells in TNBC, demonstrate the efficacy of a highly selective FZD7-ADC, and highlight the translational utility of organoid models in preclinical cancer research." (PMID 41218118, 2025). "At the same time, it raises important questions about the precise signaling mechanisms downstream of FZD7 and how they intersect with tumor heterogeneity, lineage hierarchies, and therapy resistance." (PMID 41218118, 2025). "Here, we demonstrate that Fzd7-expressing tumor cells drive the aggressive growth of transplanted MMTV-Wnt1 tumors and that selective targeting with a FZD7-specific antibody drug conjugate (ADC) blocks tumor growth." (PMID 41218118, 2025). "The mechanistic underpinnings of FZD7 function in tumor-initiating basal cells remain incompletely understood." (PMID 41218118, 2025). "Having established that Fzd7 is expressed on a subset of tumor cells, the Cd49f-positive basal-like population, we next sought to investigate the tumorigenic potential of cells expressing high vs. low levels of hFzd7 (hFzd7Hi and hFzd7Lo, respectively)." (PMID 41218118, 2025). "Tumor-derived 3D organoids recapitulate in vivo complexity and provide a platform to evaluate FZD7-dependent growth and drug response." (PMID 41218118, 2025).